POLE (DNA polymerase epsilon, catalytic subunit)
Diseases named in the same sentence as POLE in open-access papers (continued):
Sharing a sentence is not in itself a finding about the gene and the disease.
tumor (continued). "However, among the class III gene mutation testing results, the genes with higher abundance mutations include MKNK1, POLE, RET, RTEL1, RUNX1T1, TAP1, indicating that these gene mutations may be related to sex-cord-stromal tumors or require further research to explore unknown tumor subtypes." (PMID 40901169, 2025). "Additionally, the POLE P286R mutant also increases cGAS level, promotes TBK1 phosphorylation, and stimulates inflammatory gene expression and anti-tumor immune response." (PMID 38238314, 2024). "Mutations in immunotherapy-related gene panels like POLE and POLD1 both tested positive, while the expressions of PD-L1 in tumor lesions were negative." (PMID 39007151, 2024). "Here, we performed a retrospective analysis of 447 genomic profiles of tumors with POLE mutations to investigate the effect of co-occurring POLE non-pathogenic variants on TMB, and other tumor molecular features, and POLE protein stability." (PMID 38282550, 2024). "Some gene mutations, such as BRCA, ATM, and POLE/POLD1, are not conducive to the prognosis of tumour diseases but are beneficial to immunotherapy." (PMID 39530091, 2024). "POLE/POLD1 mutant tumors are recognized by the immune system, making the tumor immunogenic." (PMID 37108738, 2023). "Only one E972G mutation in an MSS tumor was not located in the exonuclease domain and the TMB in this case was relatively lower (79.5 muts/Mb) than that in cases of POLE mutations in the exonuclease domain (TMB range, 121.1595.5 muts/Mb)." (PMID 34026601, 2021). "Consistently, we found that IK mutations were associated with increased tumor mutation burden independent of mutations of BRCA and POLE, two DNA repair genes associated with tumor mutation burden in EC." (PMID 34065218, 2021). "Additionally, although the examined number of POLE-mutant tumours was small, the number of CD8-positive cells increased in tumours with partial methylation in the MLH1 gene." (PMID 34034807, 2021). "High POLE expression was associated with increased MIB-1 (encoded Ki-67), a proliferation marker, as well as high expression of cancer testis antigens (CTAs), tumor mutation burden (TMB), silent mutation rate, and non-silent mutation rate (all p < 0.001)." (PMID 32433714, 2020). "BER, MMR, FA, and DNACHK mutations as well as mutations in POLE/POLD1 were only significantly associated with longer overall survival in unadjusted analyses, but not after adjustment for TMB or tumor type." (PMID 32676589, 2020). "This study also provides a unique opportunity to conduct translational research analyses on pretreatment and post-treatment tumour tissue samples and blood samples from dMMR/MSI-H or POLE mutant CRC patients treated with the immune checkpoint inhibitor avelumab." (PMID 32079623, 2020). "Comparing the POLE-only and E/Q/Z mutant cancers did not reveal a significant difference in tumor stage, but differed in the frequency of MSI cases (p < 0.001)." (PMID 32838755, 2020). "We had available WES data obtained from four other MMR proficient CRC tumors that did not present germline or tumor alterations in POLE or POLD1 to compare their number of substitutions and mutational spectrum with our POLE mutant." (PMID 28423643, 2017).
tumor (continued). "The presence of high numbers of CD8+ and PD-1+ cells in POLE-mutant and MSI tumors may suggest the presence of high numbers of tumor-specific T cells targeting neoantigens within these subgroups of patients." (PMID 28344870, 2017). "Only one POLE-mutated tumor harbored a SOX17 mutation and this mutation was likely not mutational noise secondary to the POLE defect since it was not a TCT>TAT or TCG>TTG transition." (PMID 28978154, 2017). "Clinical tests reported the tumour to be MSS and Epstein Barr negative and to not carry any mutations in the POLE gene, thus meaning carrying all the biomarkers that so far have been identified as negative predictors of response to immunotherapy." (PMID 28758114, 2017). "Further evaluation of her tumor failed to reveal an underlying mismatch repair (MMR), DNA excision repair, and POLE or POLD mutations." (PMID 28028924, 2017). "There was no tumor recurrence after curative resection among 6 POLE-mutated EOCRC patients, in contrast with 8 out of 22 POLE-wild-type EOCRC patients." (PMID 27612425, 2016). "In humans, some, but not all, tumours from patients with germline POLE or POLD1 mutations show LOH, although data on other forms of ‘second hit’ are lacking in these tumours." (PMID 23447401, 2013). "Moreover, some APC mutations that are generally rare in CRCs are relatively common in POLE- and POLD1-mutant tumours, an example being the Arg1114X change." (PMID 23447401, 2013). "POLE and POLD1 are not classical tumour suppressor genes, as loss-of-function mutations appear not to be pathogenic." (PMID 23447401, 2013). "We note that POLE is not included in the AmpliSeq panel, so we could not definitely exclude this as a driver mutation in the MSS high tumour burden samples." (PMID 35740599, 2022). "To determine whether POLE expression is altered in HCC samples compared with normal liver tissue, we performed IHC staining analysis of tissues from the 130-patient Renji cohort, and increased POLE was found in tumor tissues." (PMID 35812186, 2022). "Hence, digenic inheritance should be considered and systematically analyzed in all childhood/AYA cancer patients in whom an identified heterozygous germline MMR gene or POLE/POLD1 PV does not alone explain the age of tumor onset and/or phenotype." (PMID 36291559, 2022). "Surprisingly, a tumor carrying a variation of unknown significance (VOUS) in POLE (p.L1327M) that has never been reported previously, also displayed a high TMB of 133.07 muts/Mb." (PMID 33726687, 2021). "Furthermore, PEG3 mutation was significantly associated with high TMB and inferior prognosis, and the associations were independent of multiple confounding factors including age, tumor stage and mutations of BRCA1, BRCA2 and POLE." (PMID 32729618, 2020). "Cancers with mutations in POLE and POLQ (E/Q), POLE and POLZ/REV3L (E/Z) and in all 3 polymerases (E/Q/Z) were associated with the highest mutation burden and an excellent prognosis independent of MSI status and tumor stage." (PMID 32838755, 2020). "Tumor WES revealed a major contribution of COSMIC mutational signature 6 (56.2%), associated with MMR deficiency, and complete absence of the POLE-associated COSMIC mutational signature 10, or signature 14, identified in tumors with concurrent POLE mutation and MMR deficiency." (PMID 32635641, 2020). "Additionally, no significant impact of tissue distribution was found in POLE category and common hypermutator tumours." (PMID 29880869, 2018). "Likewise, PD-L1 expression in tumor cells was not significantly different between POLE-wild-type and POLE-mutant tumors." (PMID 27612425, 2016).
tumor (continued). "Second hits in POLE have been reported (Cancer Genome Atlas Network) in some CRC tumours which could imply a tumour suppressor activity of the gene but the question whether POLE act as a classical tumour gene is not yet clear." (PMID 24788313, 2014). "Given the prognostic homogeneity of POLEmut cases, POLE mutation status adds minimal independent predictive value beyond classical clinicopathological features (early FIGO stage, absent/subfocal LVSI, small tumor size, preserved hormone receptors, negative peritoneal cytology, etc.)." (PMID 41536692, 2026). "Interestingly, SAMHD1 putative cancer drivers are not found in any of the POLE-P286R tumours from a collection containing 2188 non-redundant samples from 10 colorectal and endometrial studies, suggesting that these mutations might be mutually exclusive." (PMID 34228709, 2021). "Similar to this distinct genetic mutation pattern, although the mean methylation score in POLE-mutant tumours was similar to that in the MSI-U and non-MSI groups, POLE mutations may also cause a distinct pattern of epigenetic alterations in cancer-associated genes." (PMID 34034807, 2021). "The criteria for potential treatment beyond MMR/MSI testing and POLE/POLD1 are unclear, but data from the NICHE trial suggest that immunotherapy may have the potential for complete response in dMMR tumours and at least partial response in some pMMR tumours with higher levels of CD8+ T cells." (PMID 34694371, 2021). "POLE and POLD1 are currently not considered classical tumor suppressor genes, and LOH is typically not observed in tumors." (PMID 37095444, 2023). "Here, a low positive correlation was found between DLL3 tumor expression and PD-L1 CPS (%) (ρ = 0.188; p = 0.04) as well as a low negative correlation with POLE nuclear expression (%) (ρ = −0.233; p = 0.016)." (PMID 37893184, 2023). "We propose that TMB instead may be a good surrogate biomarker for MSI, as a range of 30–80 mut/Mb is typically seen in MSI tumours, as opposed to MSS POLE/POLD1 tumours, which typically have greater than 150 mut/Mb." (PMID 32306292, 2020). "POLE and POLD1 may not to act as classical tumor suppressor genes." (PMID 24583393, 2014).
cancer (315 papers, 2013 to 2026). A tumor composed of atypical neoplastic, often pleomorphic cells that invade other tissues. "POLe mutations located primarily in the proofreading domain cause replication errors and increase mutation burden in cancer cells." (PMID 40806338, 2025). "Four patients (17%) showed a complete pathological response, 50% of these patients were MSI, and the other 50% were ultramutated cancers with a POLE mutation." (PMID 40647424, 2025). "POLE-mutated (POLEmut) ECs are usually high-grade, ultramutated cancers most commonly of endometrioid histology." (PMID 40958870, 2025). "Future studies will focus on characterizing the impact of rare POLE and POLD1 mutations, such as the described POLE E1977* variant, to somatic hypermutation in cancer." (PMID 40575172, 2025). "Germline and somatic POLE/POLD1 mutations compromising the polymerase fidelity cause cancers with high mutational burden." (PMID 41263451, 2025). "When POLE is mutated, cells collect too many errors, but this also makes the cancer more visible to the body’s immune system." (PMID 40710181, 2025). "This analysis highlights the importance of POLe mutations in driving cellular transformation and immortalization in human cancers." (PMID 40806338, 2025). "The specific combination of genes associated with POLE mutations can impact the type of cancer that develops, the resulting diagnosis, and the appropriate treatment strategies." (PMID 40710181, 2025). "POLE is involved in DNA replication process and has been recently recognized as an inherited gene able to predispose to cancer." (PMID 40936703, 2025). "Somatic POLE/POLD1 mutations occur across many cancer types, but are particularly frequent in colorectal and endometrial cancer and in brain tumours of children with constitutional DNA mismatch repair deficiency (CMMRD)." (PMID 41263451, 2025). "A large pan-cancer cohort study identified POLE/POLD1 mutations as independent predictors of ICI response across solid tumors, with affected patients demonstrating higher ORR and improved survival." (PMID 41019039, 2025). "Certain POLe frameshift mutations that affect the proofreading domain are purified in cancer cells, but point mutations in other domains have also been reported." (PMID 40806338, 2025). "We have described a 56-year-old female patient diagnosed with POLE-mutated Lymphoepithelioma-like Carcinoma with Carcinosarcoma of the Endometrium (LELCCSE)." (PMID 40761799, 2025). "According to previous studies, POLE mutation was significantly associated with immunotherapy in pan-cancers; however, further validation with a larger patient cohort is required to establish this relationship with certainty at the NCI." (PMID 38916736, 2024). "Nonetheless, the selective activation of the cGAS-STING pathway and the stimulation of cancer-cell-intrinsic immunity by POLE mutations provide a theoretical-foundations for accurate molecular typing and personalized therapy of malignant tumors." (PMID 38238314, 2024). "In particular, the family of subject 4 with a POLE mutation exhibits a significant cancer history from both maternal and paternal lines, thus emphasizing the importance of studying the entire family history to select subjects eligible for testing." (PMID 39001389, 2024). "The PER-POLE-P286R error signature best corresponds to profiles of cancer samples where MMR loss precedes the acquisition of the POLE mutation." (PMID 39390083, 2024). "In the first stage, in patients with histologically confirmed endometrioid, serous, and clear cell endometrial cancer, the presence of POLE mutations in cancer cells is determined." (PMID 39518001, 2024).
cancer (continued). "A recent report has evidenced that cancer-associated POLE alleles can lead to a mutator phenotype even when MMR is functional." (PMID 37891003, 2024). "Cancers often develop in individuals with constitutional MMRD as a result of early somatic-driver mutations in POLE or POLD1." (PMID 39204096, 2024). "As a consequence of this research, the prognostic value of specific mutations in the POLE gene, so called “hotspot mutations,” has recently recognized, and this has revolutionized the management of endometrial and other cancers." (PMID 39239272, 2024). "On the contrary, the P286R mutation in exon 9 of the DNA polymeraseε(POLE) gene activates intrinsic immunity in cancer cells and suppresses the occurrence of endometrial tumors via the cGAS-STING pathway." (PMID 39445027, 2024). "African American women are less likely to have POLE ultra-mutated cancers, which tend to have a better prognosis." (PMID 38539507, 2024). "Rare cancer subgroups can also provide important insights into tumorigenesis, as exemplified by POLE driver mutations." (PMID 39112709, 2024). "Cancer patients in whom the suspected diagnosis of CMMRD cannot be confirmed should probably be tested for germline POLE and POLD1 exonuclease domain variants (Rec." (PMID 39420201, 2024). "An analysis of a database of 47721 patients with different types of cancer found that patients with POLE/POLD1 mutations nearly doubled their OS after immunotherapy as compared with those with wild-type disease." (PMID 39530091, 2024). "For example, P286R and V411L, which are the two most frequent POLE mutations in cancer inducing high TMB, show very different impacts of the mutation rate in haploid and diploid yeast." (PMID 37891003, 2024). "In a retrospective analysis of patients with various cancer types, pathogenic mutations in POLE were associated with clinical benefit to ICI." (PMID 38280045, 2024). "Cluster 2 contains the remaining samples which also have less than 20% of POLE-exo-specific variants, representing 12 different cancer types." (PMID 36829160, 2023). "P286R and V411L are the two DNA Polymerase ε (POLE) variants that are the most frequent somatic variants associated with hypermutated cancer cells." (PMID 37592814, 2023). "Previous studies investigating the association of POLE/POLD1 mutation with MSI status in various cancers have shown ambiguous results." (PMID 36980791, 2023). "The mORI detection method is applicable to cells characterized by the POLE mutator phenotype, which currently is only associated with cancer." (PMID 36829160, 2023). "Their analysis demonstrated that among ICI-treated cancer individuals, patients with either POLE or POLD1 mutations have significantly longer overall survival in comparison with those without." (PMID 36980791, 2023). "Recent studies using yeast have also provided insight into the possible functional consequences of V411L, the second most common POLE mutation in cancer." (PMID 37388540, 2023). "This large difference is intriguing because P286R and V411L are the two most frequent POLE mutations in cancer and tumors from both have high TMB." (PMID 37388540, 2023). "Cancer genome sequencing studies uncovered recurrent somatic mutations in POLE from somatic human tumors." (PMID 37388540, 2023). "Another TCGA study suggested that cancers carrying POLE mutations were good candidates for immune checkpoint inhibitor therapy." (PMID 37417594, 2023). "In the context of immunotherapy, Tumor Mutation Burden (TMB) in the DNA polymerase epsilon (POLE) subtype of this cancer holds promise as a viable therapeutic target." (PMID 37525139, 2023). "In our study, we found a parallel tendency of a TMB increase between SETD2 deleterious mutations and DDR gene mutations including BRCA1/2, MMR genes, and POLE/D1 across seven cancer types." (PMID 37479966, 2023).